PRDM6 (PR/SET domain 6)
Description:
Putative histone methyltransferase that acts as a transcriptional repressor of smooth muscle gene expression. Promotes the transition from differentiated to proliferative smooth muscle by suppressing differentiation and maintaining the proliferative potential of vascular smooth muscle cells. Also plays a role in endothelial cells by inhibiting endothelial cell proliferation, survival and differentiation. It is unclear whether it has histone methyltransferase activity in vivo. According to some authors, it does not act as a histone methyltransferase by itself and represses transcription by recruiting EHMT2/G9a. According to others, it possesses histone methyltransferase activity when associated with other proteins and specifically methylates 'Lys-20' of histone H4 in vitro. 'Lys-20' methylation represents a specific tag for epigenetic transcriptional repression.
Synonyms: PRISM; KMT8C; PDA3
Tractability: PROTAC: ubiquitination databases record sites on it.
Target class: Enzyme; Transferase
Gene: Protein-coding gene on chromosome 5 (123,089,241 to 123,194,266, forward strand). Ensembl gene ENSG00000061455.
Subcellular location: Nucleus
Subcellular location (Human Protein Atlas): Nucleoplasm
Gene Ontology:
Molecular function: identical protein binding; protein binding; histone H4K20 monomethyltransferase activity; histone methyltransferase activity
Biological process: negative regulation of transcription by RNA polymerase II; regulation of gene expression; chromatin remodeling; negative regulation of DNA-templated transcription
Cellular component: nucleus
Genetic constraint (gnomAD): Loss-of-function variants: 25 observed, 53.78 expected, observed/expected ratio (o/e) 0.46, 90% interval 0.34 to 0.65. The synonymous counts are far from expectation, so gnomAD's model fits this gene poorly and the ratio says little. Missense variants: 831 observed, 752.31 expected, observed/expected ratio (o/e) 1.1, 90% interval 1.04 to 1.17. Synonymous variants: 405 observed, 328.53 expected, observed/expected ratio (o/e) 1.23, 90% interval 1.14 to 1.34.
Homologues: Orthologues: chimpanzee PRDM6 (99% identical), macaque PRDM6 (99% identical), pig PRDM6 (96% identical), mouse Prdm6 (95% identical), rat Prdm6 (91% identical), dog PRDM6 (91% identical), tropical clawed frog prdm6 (77% identical), rabbit PRDM6 (74% identical), guinea pig PRDM6 (57% identical). Paralogues in human: PRDM14 (24% identical), HIC2 (12% identical), PRDM1 (12% identical), PATZ1 (11% identical), HIC1 (11% identical), ZBTB16 (11% identical), ZNF281 (11% identical), ZNF362 (11% identical), ZNF692 (10% identical), ZNF384 (10% identical), MTF1 (10% identical), ZNF653 (10% identical), and 24 more.
Diseases named in the same sentence as PRDM6 in open-access papers:
PRDM6 is named in the same sentence as 27 diseases in open-access papers, as found by Europe PMC text mining. Sharing a sentence is not in itself a finding about the gene and the disease. The quoted sentences say what the papers report.
medulloblastoma (14 papers, 2017 to 2025). A malignant, invasive embryonal neoplasm arising from the cerebellum. "The upregulation of PRDM6 expression in Group 4 medulloblastoma is thought to occur via enhancer hijacking caused by tandem duplication of SNCAIP, which is located approximately 600 kb upstream of PRDM64." (PMID 38992221, 2024). "In conclusion, our work provides further evidence for the high heterogeneity of variants seen across G4 medulloblastoma and adds new complex events including a new mechanism of PRDM6 overexpression via gene duplication." (PMID 37576901, 2023). "Furthermore, PTCH1, DDX3X and SMO driver mutations characteristic to SHH medulloblastomas, and PRDM6 enhancer hijacking driver events found in Group 4-medulloblastomas associated with MuAt features (FDR<1%)." (PMID 37420249, 2023). "Structural variants affecting SNCAIP disrupt the local chromatin environment, promoting abnormal gene induction, particularly PRDM6 in medulloblastoma." (PMID 39140252, 2025). "We propose that both PRDM6 and additional factors, such as specific cell-of-origin features, are required for Group 4 medulloblastoma." (PMID 38992221, 2024). "Our findings that PRDM6 expression in hindbrain neuroepithelial stem cells promotes medulloblastoma indicate that PRDM6 can indeed function as a medulloblastoma driver." (PMID 38992221, 2024). "For medulloblastoma, we found SVs in noncoding regions that caused super-enhancer hijacking events of medulloblastoma driver genes (GFI1, GFI1B, and PRDM6)." (PMID 39322849, 2024). "Surprisingly, medulloblastomas derived from PRDM6-expressing neuroepithelial stem cells match human Group 3, but not Group 4, medulloblastoma." (PMID 38992221, 2024). "Because a subset of Group 4 medulloblastomas shows high expression of PRDM6 in conjunction with amplification of the MYCN oncogene, we decided to investigate potential synergies between PRDM6 and MYCN expression on tumor development from NES cells." (PMID 38992221, 2024). "Here, we investigated the function of PRDM6 in human hindbrain neuroepithelial stem cells and tested PRDM6 as a driver of Group 4 medulloblastoma." (PMID 38992221, 2024). "We conclude that PRDM6 expression has oncogenic potential but is insufficient to drive Group 4 medulloblastoma from neuroepithelial stem cells." (PMID 38992221, 2024). "To assess if PRDM6 is a driver of Group 4 medulloblastoma, we set out to elucidate the functional impact and oncogenic potential of sustained PRDM6 expression in human neuroepithelial stem (NES) cells." (PMID 38992221, 2024). "MuAt stratified medulloblastomas into four clusters, one of which contained seven tumours driven by enhancer hijacking events involving PRDM6 with a 3.7-fold increase in SV burden." (PMID 37420249, 2023). "PRDM6 has been described as having the ability to alter chromatin structure and gene expression in human neuroepithelial stem cells, hence increasing the development of medulloblastoma." (PMID 41155227, 2025). "Given the oncogenic potential of PRDM6 we report here, its inhibition may be of benefit in PRDM6-expressing Group 4 medulloblastomas." (PMID 38992221, 2024). "However, we conclude that additional factors are required for Group 4 medulloblastoma formation as PRDM6 NES cell-derived tumors most closely resemble Group 3 medulloblastoma." (PMID 38992221, 2024). "Complex SVs in the noncoding region near PRDM6 were also reported in group 4 medulloblastomas in a previous study, whereas neo-TAD formation by complex SVs remains unclear." (PMID 39322849, 2024). "Our observations may provide clues as to how PRDM6 expression promotes medulloblastoma formation from NES cells." (PMID 38992221, 2024). "Local SV clusters around PRDM6 found in the patient with medulloblastoma are one such case." (PMID 39322849, 2024). "SNCAIP duplication may promote Group 4 medulloblastoma via induction of PRDM6, a poorly characterized member of the PRDF1 and RIZ1 homology domain-containing (PRDM) family of transcription factors." (PMID 38992221, 2024).
medulloblastoma (continued). "Mutually exclusive mutations in group 4 medulloblastomas could be attributed to the effect of the core binding factor (CBFA) and include CBFA2T2, CBFA2T3, PRDM6, UTX, and OTX2 genes." (PMID 36829544, 2023). "Interestingly, medulloblastomas with PRDM6 driver alterations (n=7) were confined to one of MuAt feature clusters." (PMID 37420249, 2023). "In the G4 medulloblastomas, SVs affecting GFI1 and GFI1B and the recurrent tandem duplication of SNCAIP are known to cause overexpression of GFI1, GFI1B and PRDM6, respectively, by putting them under the control of super-enhancer regions (termed enhancer hijacking, EH)." (PMID 37576901, 2023). "PRDM6 is activated by enhancer hijacking events in Group 4 medulloblastomas." (PMID 37420249, 2023). "Notably, we found complex SVs in the noncoding region in the driver mutation-negative case (PD2107), which included a subtype-specific SE of group 4 medulloblastomas near the PRDM6 gene, the overexpression of which has been suggested as a driver of medulloblastoma." (PMID 39322849, 2024). "Moreover, we show that PRDM6 expression in neuroepithelial stem cells promotes medulloblastoma." (PMID 38992221, 2024). "Several, not mutually exclusive reasons may underlie why PRDM6 NES cell-derived medulloblastomas do not recapitulate Group 4 medulloblastomas." (PMID 38992221, 2024). "Nevertheless, it has been showcased that PRDM6 targets the histone marks, including H3K27, in medulloblastoma." (PMID 40936897, 2025). "Group 3/4 medulloblastoma with MYC, MYCN or PRDM6 alterations have complex subclonal structures, with each subclone having unique properties." (PMID 40335697, 2025). "Together, our findings show that PRDM6 expression in NES cells has oncogenic potential and promotes medulloblastoma formation." (PMID 38992221, 2024). "H3K27me3 affects the spatiotemporal control of gene expression in complex ways, so it will be important to interrogate interplays between H3K27 methylation and PRDM6 in NES cells and medulloblastoma." (PMID 38992221, 2024). "Further, the role of PRDM6 expression in the etiology of Group 4 medulloblastoma or other brain cancers has not been tested." (PMID 38992221, 2024). "We detected several enhancer-hijacking events, an ecDNA containing the MYCN gene, and rare structural rearrangements, such a chromothripsis in a G4 medulloblastoma, chromoplexy involving 8 different chromosomes, a TERT gene rearrangement, and a PRDM6 duplication." (PMID 37576901, 2023). "Given the lack of PRDM6 expression in normal tissues and its oncogenic potential shown here, we suggest that PRDM6 inhibition may have therapeutic value in PRDM6-expressing medulloblastomas." (PMID 38992221, 2024). "Tumors derived from PRDM6 NES cells clustered most closely with Group 3 medulloblastomas and showed no similarity with pediatric non-medulloblastoma CNS tumors." (PMID 38992221, 2024).
Patent ductus arteriosus (6 papers, 2019 to 2025). In utero, the ductus arteriosus (DA) serves to divert ventricular output away from the lungs and toward the placenta by connecting the main pulmonary artery to the descending aorta. "PRDM6 regulates vascular smooth muscle cell differentiation, with variants linked to patent ductus arteriosus, CAD and AF." (PMID 41172738, 2025). "Further supporting the importance of Prdm6 in SMCs in human cardiovascular disease, a genetic study described Prdm6-coding mutations that were associated with patent ductus arteriosus (DA)." (PMID 36749647, 2023). "PRDM6 is associated with isolated nonsyndromic patent ductus arteriosus, while ZFP28 plays an essential role in controlling gene expression during cardiac and vascular pathogeneses." (PMID 33466592, 2021). "A recent study found that various independent loss-of-function mutations in PRDM6 were associated with patent ductus arteriosus (PDA)." (PMID 30819207, 2019). "Alterations in PRDM6 might influence AAomax through regulation of vascular smooth muscle cells contractile proteins or through its association with patent ductus arteriosus." (PMID 34968759, 2022). "Mutation of PRDM6 has been linked to the congenital heart defect, patent ductus arteriosus." (PMID 30819207, 2019). "In an effort to deduce the disease mechanism of non-syndromic patent ductus arteriosus (PDA), combine genome-wide linkage analysis and WES study identified independent missense mutations in PRDM6." (PMID 33803261, 2021).
Hypertension (5 papers, 2021 to 2024). The presence of chronic increased pressure in the systemic arterial system. "PRDM6-encoded protein is a histone modifier that is exclusively expressed in smooth muscle cells (SMCs) in adult life, reaching its highest levels in the SMCs of the aorta and other arteries and is, therefore, a great candidate gene for arterial hypertension." (PMID 36602864, 2023). "The present study showed that PRDM6 methylations were associated with BP and hypertension." (PMID 35087571, 2021). "Strikingly, mice with heterozygous SMC deletion of PRDM6 (Prdm6fl/ + SM22-Cre) developed hypertension when subjected to a high salt diet." (PMID 38691164, 2024). "A recent study by our group identified PRDM6 (PRDI-BF1 and RIZ homology domain-containing protein 6) as the causal gene for hypertension at the 5q23 locus using massively parallel reporter and gene editing assays." (PMID 38691164, 2024). "The heterozygous SMC-specific Prdm6-knockout mice develop hypertension in response to a high-salt diet." (PMID 36602864, 2023). "Taken together, these findings identify PRDM6 as a hub for a network of genes that regulate BP and characterize PRDM6 as a critical regulator for renin-dependent hypertension." (PMID 36602864, 2023). "Strikingly, hypertension developed only when PRDM6 was disrupted embryonically, indicating the developmental role of PRDM6 in BP regulation." (PMID 36602864, 2023). "By combining fine mapping, massively parallel reporter assays, and gene editing, we identified super enhancers that drive the expression of PRDM6 and are partly regulated by STAT1 as the causal variants for hypertension." (PMID 36602864, 2023). "In conclusion, we believe that our study establishes the role of PRDM6 as a master regulator of BP and as an attractive target for the treatment of hypertension." (PMID 36602864, 2023). "We then demonstrated a link between reduced PRDM6 transcript levels and the development of hypertension in vivo." (PMID 36602864, 2023). "In summary, the present study showed that DNA methylation in the promoters of PRDM6, HDAC9, IGFBP3, LRRC10B, SYT7, PDE3A, TBX2 and C17orf82 genes were significantly associated with BP or hypertension." (PMID 35087571, 2021). "We found that DNA methylations in the promoters of PRDM6, HDAC9, IGFBP3, SYT7, TBX2 and C17orf82 were significantly associated with BP or hypertension in the Chinese Han population." (PMID 35087571, 2021). "Methylation levels of PRDM6 and SYT7 were significantly associated with hypertension." (PMID 35087571, 2021). "Therefore, among the test DNA methylations, methylations in PRDM6 were significantly associated with both DBP and hypertension." (PMID 35087571, 2021). "SMC-specific depletion of Prdm6 in adult mice did not affect BP or the development of hypertension." (PMID 36749647, 2023).
breast carcinoma (3 papers, 2015 to 2022). "Four additional V loci were identified from looking up MD and breast cancer susceptibility SNPs in GWAS of V, including 5q23.2 (PRDM6), 8p21.2 (EBF2), 12p12.1 (SSPN), and 16q12.2 (FTO)." (PMID 36344993, 2022). "Four additional loci for MD or breast cancer risk, 5q23.2 (PRDM6), 8p21.2 (EBF2), 12p12.1 (SSPN), and 16q12.2 (FTO), were also found associated with V." (PMID 36344993, 2022).
Obesity (2 papers, 2019 to 2020). Accumulation of substantial excess body fat. "Many studies have proven specific associations between histone methylation and growth and obesity; therefore, the PRDM6 gene might affect goat growth and development by being associated with histone methylation." (PMID 32012655, 2020). "Recently, some reports found that the PRDM6 gene acted as a potentially pleiotropic gene associated with osteoporosis and obesity, which illustrates that it may participate in regulating growth and development in various ways." (PMID 32012655, 2020).
brain tumors (1 paper, 2024). "The patient also showed overexpression of PRDM6 with a 90-fold change in FPKM compared to that in our cohort of brain tumors, suggesting that complex SVs may induce PRDM6 overexpression." (PMID 39322849, 2024).
congenital heart disease (1 paper, 2022). A heart disease that is present at birth. "Altogether, these findings revealed Prdm6 as a key regulator of CNCC differentiation and migration and identified Prdm6 and its regulated network as potential targets for the treatment of congenital heart diseases." (PMID 35108221, 2022). "The characterization of Prdm6 function in NCCs has, therefore, a broad implication for the pathogenesis of inherited and acquired congenital heart diseases and may lead to identification of novel targets for drug development." (PMID 35108221, 2022).
heart failure (1 paper, 2013). Inability of the heart to pump blood at an adequate rate to meet tissue metabolic requirements. "Alternatively, however, it cannot be ruled out that SM22-driven deletion of Prdm6 in cardiomyocytes during early development eventually causes heart failure in newborn mice with subsequent secondary blood congestion and hemorrhage in the lungs." (PMID 24278461, 2013).
intrauterine growth restriction (1 paper, 2019). "Alterations in this tissue have been associated with multiple adverse pregnancy outcomes including intrauterine growth restriction and impaired infant neurodevelopment, suggesting that the observed reduction in placental PRDM6 expression may have a range of adverse effects on infant health." (PMID 30819207, 2019).
ischemic stroke (1 paper, 2022). A stroke disorder caused by obstruction of blood flow to the brain, due to thrombotic (local blood clot formation) or embolic (due to a blood clot or other material traveling from another site) event. "Based on this information, it seems that the identified DNA methylation may have the potential to regulate gene expression, and higher methylation levels of the PRDM6 gene may lead to lower expression levels of PRDM6 and contribute to a lower risk of ischemic stroke." (PMID 35345488, 2022). "Methylation of AMH, C17orf82, HDAC9, IGFBP3, LRRC10B, PDE3A, PRDM6, SYT7 and TBX2 was significantly associated with ischemic stroke." (PMID 35345488, 2022). "We found that PRDM6 was differentially expressed between ischemic stroke cases and controls by analyzing data in the GEO database." (PMID 35345488, 2022). "Higher methylation levels of 18 targets in AMH, C17orf82, HDAC9, IGFBP3, LRRC10B, PDE3A, PRDM6, SYT7 and TBX2 genes were associated with a lower risk of ischemic stroke." (PMID 35345488, 2022). "According to the results from stage one and stage two, we confirmed that higher methylation levels of 17 targets in AMH, C17orf82, HDAC9, IGFBP3, LRRC10B, PDE3A, PRDM6, SYT7 and TBX2 genes were associated with a lower risk of ischemic stroke." (PMID 35345488, 2022). "The expression levels of PRDM6 were higher in ischemic stroke patients than in controls." (PMID 35345488, 2022). "The results showed that the mean methylation levels of AMH, C17orf82, HDAC9, IGFBP3, LRRC10B, PDE3A, PRDM6, SYT7 and TBX2 were significantly (Wilcoxon's two sample test) lower in ischemic stroke cases than in controls." (PMID 35345488, 2022).
Pca (1 paper, 2022). "The results showed that the higher expression levels of JAZF1, PRDM6, RBMS3, and TSHR were correlated with the poor prognosis of Pca patients." (PMID 35959113, 2022). "In the regulatory networks of target genes of the sDMIRs, we found that JAZF1, PRDM6, RBMS3, and TSHR were correlated with the poor prognosis of PCa patients." (PMID 35959113, 2022).
Pulmonary hemorrhage (1 paper, 2013). Pulmonary hemorrhage is a bleeding within the lungs. "The cardiovascular phenotype that we observe in the Prdm6del/del total knockout embryos and pulmonary hemorrhage that we observe in the SM22-Cre driven conditional deletion of Prdm6 are in line with the reported physiological expression of Prdm6 within the vascular system." (PMID 24278461, 2013).
renal cell carcinoma (1 paper, 2022). "When looking at the top 10 upregulated genes, we found for example Ccdc180, Col11a1, Gria2, or Prdm6 in males in relation to regulation of transcription, renal cell carcinoma, and fibrosis." (PMID 35230975, 2022).
respiratory failure (1 paper, 2013). The significant impairment of gas exchange within the lungs resulting in hypoxia, hypercarbia, or both, to the extent that organ tissue perfusion is severely compromised. "Moreover, deficiency of Wnt7b results in postnatal death due to lung hemorrhage caused by vascular leakage and subsequent respiratory failure, similar to what we observed upon selective Prdm6 deletion in SMCs using SM22-Cre." (PMID 24278461, 2013).